INS (insulin)
Diseases named in the same sentence as INS in open-access papers (continued):
Sharing a sentence is not in itself a finding about the gene and the disease.
type 1 diabetes (continued). "Since its discovery in 1921, injectable insulin remains the mainstream treatment for treating type 1 diabetes and although effective, its route of administration remains problematic in terms of patient compliance, injection complications, and storage challenges." (PMID 34572086, 2021). "Type 1 diabetes results from the failure of the beta cells in pancreas to produce enough insulin." (PMID 33788062, 2021). "Carbohydrate counting, a system by which the insulin dose is calculated based upon the planned number of carbohydrates to be consumed, became widely popularized in the 2010s to increase dietary choice and flexibility for individuals with type 1 diabetes." (PMID 33828529, 2021). "Subgroup analysis of changes (Δ) of anthropometric, performance and metabolic parameters based on response to changes in whole-body insulin sensitivity and PA participation over 5 years for patients with type 1 diabetes, divided into Q1 (n=9), Q2 (n=5), Q3 (n=33) and Q4 (n=34)." (PMID 34659107, 2021). "However, we did observe a positive correlation between BMI and insuline dose/kg bodyweight, suggesting that exogenous insulin is more important than the ghrelin system in the development of obesity in type 1 diabetes." (PMID 34294136, 2021). "Last, we used the publicly available OhioT1DM Dataset to explore whether CGM-based prediction models would translate to individuals with type 1 diabetes, the primary target population for closed-loop insulin delivery." (PMID 34166426, 2021). "As previously reported individuals with type 1 diabetes continuously secrete plasma glucagon after 14 hours of insulin withdrawal despite mean plasma‐glucose of around 20 mmol/L; and following intravenous insulin infusion glucagon concentrations are suppressed." (PMID 34405569, 2021). "A recent systematic review and meta-analysis about safety of Ramadan fasting in type 1 diabetes suggests that fine-tuning of insulin therapy by the use of pump infusion and intensive glucose control may mitigate hypoglycaemia risk." (PMID 33683423, 2021). "However, there is currently no cure available for type 1 diabetes, and most patients have to rely on lifelong insulin injection." (PMID 33690220, 2021). "Insulin has been utilized in the treatment of type 1 diabetes (T1D) for 100 years." (PMID 37745178, 2021). "Almost all patients with type 1 diabetes used insulin monotherapy (93.1%)." (PMID 34134677, 2021). "Taking into account that in people with type 1 diabetes exogenous insulin is continuously circulating that is inversely related to rates of lipolysis, safe and feasible strategies need to be defined for bodyweight and insulin resistance management." (PMID 34295305, 2021). "Those include also strategies incorporating longer fasting periods, however, data on the impact of fasting interventions on safety, namely hypoglycaemia and diabetic ketoacidosis and the change in the insulin dose needed following a prolonged fasting period in people with type 1 diabetes are scarce." (PMID 34295305, 2021). "Thus, the aim of this study was to examine the effects of swimming training combined with insulin therapy on the femoral cortical bone structural and mechanical properties in growing rats with type 1 diabetes." (PMID 34440530, 2021). "Type 1 diabetes (T1D) occurs due to the autoimmune destruction of beta cells, whereas type 2 diabetes (T2D) has a more complex mechanism, involving insulin resistance in peripheral tissues." (PMID 35155441, 2021). "In many instances, type 1 diabetes was identified solely on the basis of current insulin treatment." (PMID 34599655, 2021). "In type 1 diabetes, the effects of exercise on glucose levels are the result of many factors, including pre-exercise glucose values, injection site, amount of insulin administered, composition and size of the pre-exercise meal, and duration and intensity of exercise." (PMID 34948667, 2021).
type 1 diabetes (continued). "In type 1 diabetes patients, the glucoregulatory response to moderate-intensity exercise is impaired, mainly due to the absence of the secretion of physiological amounts of endogenous insulin." (PMID 34836420, 2021). "Type 1 diabetes comes with the burden of extensive monitoring and insulin administration, and in turn, people living with T1D may feel less support from their families due to breaks in activity for insulin injections or glucose monitoring." (PMID 34485879, 2021). "A strength of our study is that we could examine pancreas tissue from donors with recent-onset type 1 diabetes, residual insulin-positive islets and ongoing autoimmunity." (PMID 33912981, 2021). "Insulin has been lifesaving for patients with type 1 diabetes." (PMID 34684300, 2021). "For this reason, people with type 1 diabetes will require daily insulin administration for life." (PMID 33810048, 2021). "Type 1 diabetes is a chronic autoimmune disease characterized by inflammatory response against pancreatic islets, consequently resulting in progressive β-cell destruction and defective insulin secretion." (PMID 34054343, 2021). "Recently, type 1 diabetes mellitus (T1DM) is a multifactorial autoimmune disease characterized by insulin deficiency and hyperglycaemia, which is considered to involve the selective attack of insulin-producing pancreatic β cells by activated T lymphocytes that recognize their autoantigens." (PMID 34006268, 2021). "During the initial stage of type 1 diabetes, prolonged exposure of pancreatic β-cell to proinflammatory cytokines such as IL-1β, TNF-α, and IFN-γ results in a decreased capacity to produce and release insulin, as well as cell loss by apoptosis." (PMID 34054343, 2021). "The subjects with type 1 diabetes had impaired insulin-mediated free fatty acid suppression, suggesting that lipotoxicity over time may be a potential mechanistic explanation." (PMID 33828529, 2021). "In addition to insulin therapy, adequate exercise and a scrupulously maintained diet are necessary and integral components of effective treatment of type 1 diabetes." (PMID 33467392, 2021). "This study evaluated differences in outcomes for young adults in the United States (U.S.)from lower socioeconomic (SES) backgrounds with type 1 diabetes (T1D) managed on continuous subcutaneous insulin infusion (CSII) versus multiple daily injections (MDI) or fixed‐dose insulin (FDI)." (PMID 34277976, 2021). "The discovery of insulin in 1921 changed the prognosis for people with type 1 diabetes." (PMID 33483763, 2021). "The growing empathy for people with type 1 diabetes because of the high prices of insulin may be interconnected with a decline in the stigma." (PMID 33496671, 2021). "The primary objective of this randomized controlled study was to evaluate whether daily SMS reminders about insulin injections improved glycemic control in adolescents and young adults with poorly controlled type 1 diabetes." (PMID 33720997, 2021). "His C-peptide and insulin levels were low, and he was diagnosed with type 1 diabetes." (PMID 34177811, 2021). "Type 1 diabetes appeared to represent the overwhelming majority of encounters; however, clinicians in this study still seemed to prefer to record disposition according to insulin treatment, resulting in an incomplete data set." (PMID 34539249, 2021). "However, IR can also affect insulin deficient patients with type 1 diabetes (T1D) and may be associated with metabolic, macrovascular and microvascular complications." (PMID 34438601, 2021). "Given the nature of type 1 diabetes, the insulin doses overall were low and stable." (PMID 33927691, 2021). "Type 1 diabetes is one of the most common chronic conditions among children and adolescents and requires a demanding treatment regimen (e.g., insulin administration several times a day, monitoring of glucose levels and regulation of food intake and physical activity)." (PMID 34855927, 2021).
type 1 diabetes (continued). "For example, glucose clamp experiments, performed in subjects with type I diabetes, could be carried out for insulin with an evaluation of the time-of-action profile under standard conditions." (PMID 33686847, 2021). "Type 1 Diabetes (T1D) results from autoimmune destruction of insulin producing pancreatic ß-cells." (PMID 34299114, 2021). "Flexible insulin therapy is one of the fundamental elements in the management of type 1 diabetes." (PMID 33585132, 2021). "In contrast to the effects of swimming training on the femoral neck of growing rats with severe STZ-induced type 1 diabetes under insulin therapy, the benefits of insulin treatment on the femoral midshaft structural and mechanical properties were not affected by swimming training in this model." (PMID 34440530, 2021). "Besides taking insulin on a daily basis, patients with type 1 diabetes should be disciplined in carbohydrate, fat, and protein counting, persistent in eating healthy foods, and exercise regularly to maintain a healthy weight." (PMID 33467194, 2021). "Thus far data regarding the safety and efficacy of closed-loop insulin delivery in type 1 diabetes are limited." (PMID 33512267, 2021). "Indeed, data derived from clinical transplant studies in type 1 diabetes support a protective role in DR for endogenous insulin secretion." (PMID 34912295, 2021). "In another type 1 diabetes study, insulin demand declined significantly from baseline." (PMID 33957998, 2021). "Moreover, metformin is sometimes used as an adjunct agent, together with insulin, to treat patients with type 1 diabetes." (PMID 33562458, 2021). "Our results are the first to indicate that insulin treatment has a significant impact on carnitine homeostasis and may be of clinical importance in the treatment of type 1 diabetes." (PMID 34833964, 2021). "Likewise, the insulin-independent reversal of type I diabetes (T1D) was achieved when BAT from healthy mice was transplanted in the streptozotocin-induced diabetic mouse model." (PMID 33953697, 2021). "In our pediatric series, the application of algorithmic adaptations of insulin doses and carbohydrate intake has globally improved glycemic control during 15 h after real-time exercises performed by children and adolescents with type 1 diabetes." (PMID 34512541, 2021). "Type 1 diabetes is a chronic autoimmune disease requiring insulin treatment for survival." (PMID 34671071, 2021). "Due to the early onset age and the necessity of insulin treatment, most employees with type 1 diabetes may face the challenge of integrating both work and illness management for most of their time as active members of the workforce." (PMID 34803795, 2021). "Studies about Detemir and type 1 diabetes in pregnancy published in recent years showed that Detemir is as effective as NPH when used as a basal insulin in pregnant women affected by type 1 diabetes with the potential to offer some clinical benefits in terms of fasting plasma glucose control." (PMID 33767671, 2021). "In the large REducing With MetfOrmin Vascular Adverse Lesions (REMOVAL) trial, however, metformin did not reduce the long-term insulin needs or improve glycaemic control in people with long-standing type 1 diabetes and multiple cardiovascular risk factors." (PMID 33595677, 2021). "The technological development in recent years in the type 1 diabetes field has led to an increase in the use of technology, with the possibility of remote access to continuous glucose monitoring systems and insulin pump data, downloaded by patients in the comfort of their own homes." (PMID 34203306, 2021). "Because of their type 1 diabetes, all our patients lack portal insulin signaling to the liver." (PMID 34294136, 2021). "We found little evidence of the stigma associated with being on insulin among people with type 1 diabetes, which has been reported in previous studies." (PMID 33496671, 2021).
type 1 diabetes (continued). "In people with type 1 diabetes, fasting might lower the need for exogenous insulin, stabilize glucose levels in a near normoglycaemic range, lower bodyweight and body mass index (BMI) and lower the total carbohydrates intake." (PMID 34295305, 2021). "Moreover, this is the first report on adult Japanese patients with type 1 diabetes, a population prone to insulin depletion." (PMID 33597626, 2021). "In this study, young patients with type 1 diabetes who used insulin pumps were less likely to have DR independent of other risk factors." (PMID 34570208, 2021). "A 10–15 min delay in the postprandial glucose rise may also be useful in people with type 1 diabetes using subcutaneously administered insulin." (PMID 32751269, 2020). "Here, we tested the hypothesis that ghrelin also is protective against insulin-induced hypoglycemia in the streptozotocin mouse model of type 1 diabetes." (PMID 33042003, 2020). "In type 1 diabetes autoreactive T cells destroy insulin-producing β-cells in the pancreatic islets." (PMID 32753746, 2020). "Compared to insulin glargine however, insulin detemir has a shorter duration of action, and therefore may need to be given twice a day, particularly in patients with type 1 diabetes." (PMID 32396624, 2020). "Therefore, people with type 1 diabetes require careful blood glucose monitoring to detect reducing insulin requirements." (PMID 32743907, 2020). "In addition, 75 patients with type 1 diabetes were added to examine the potential the impact of subcutaneous insulin therapy on pulmonary function." (PMID 32344939, 2020). "With rapid advances in technology to treat type 1 diabetes, including the introduction of CGMs and the increasing use of insulin pumps, evaluating time trends for pregnancy and delivery outcomes could provide insights about this high-risk US population." (PMID 32488037, 2020). "On the other hand, type 1 diabetes (T1D), which is also known as juvenile diabetes, may occur as a result of autoimmune destruction of insulin-producing pancreatic β-cells." (PMID 32168855, 2020). "Interestingly, concurrent with the increase in type 1 diabetes prevalence, there have been rapid advances in technology for the purpose of improving glycemic control, including insulin pumps and continuous glucose monitors (CGM)." (PMID 32488037, 2020). "Results of the within-individual analyses were similar in the sensitivity analyses either excluding children diagnosed with type 1 diabetes before age 1 year (n = 84) or defining type 1 diabetes based on diagnosis (n = 2935) or insulin prescription (n = 3597) separately (eTable 3 in the Supplement)." (PMID 32163166, 2020). "In humans recently diagnosed with type 1 diabetes, the insulin release to increments of glucose concentrations in the lower range is also the first to be lost, suggesting a coupling of attack on beta cells to their metabolic activity, although not necessarily to their blood supply." (PMID 32618430, 2020). "Type 1 diabetes is a chronic condition of blood glucose metabolic disorder caused by a lack of insulin secretion from pancreas cells." (PMID 32784178, 2020). "Due to these concerns, delayed intensification of insulin therapy for people with type-I diabetes occurs, and adherence to injection regimens may be suboptimal." (PMID 32785196, 2020). "The viewpoint of insulin therapy differs greatly between T2D and type 1 diabetes (T1D)." (PMID 31833010, 2020). "However, a validation study has shown that those with possible type 1 diabetes adults defined by using insulin and age of onset <30 years old which has been validated as accurate in 97% of cases." (PMID 32132977, 2020). "Government officials and insurers should consider improving coverage for all type 1 diabetes–related services, following the approach of a 2019 rule allowing qualified high-deductible health plans to cover services such as insulin and glucometers before deductibles are met." (PMID 32478819, 2020).
type 1 diabetes (continued). "Furthermore, clofibrate in patients with non-insulin-dependent diabetes decreases fasting plasma glucose and insulin levels, and insulin binding to erythrocytes is enhanced because of increased insulin receptor affinity without a change in receptor number." (PMID 32708786, 2020). "We used rats with type-1 diabetes to eliminate the mediation of endogenous insulin." (PMID 33233692, 2020). "Findings suggest that substantial out-of-pocket burden may remain for patients with type 1 diabetes even if insulin cost-sharing is limited." (PMID 32478819, 2020). "Additionally, B. carterii oleo-gum resin showed an antidiabetic capacity by increasing the serum insulin, regenerating β-cells of Langerhans islets, enhancing glycogenesis, and declining glycogenolysis in rats with alloxan-induced type 1 diabetes." (PMID 33235693, 2020). "Ongoing research is increasingly focusing on the unique physiology of such high-level athletes with type 1 diabetes, while also investigating how new insulin analogues and other therapeutic agents/technologies might improve their glycaemic management." (PMID 32533229, 2020). "Type 1 diabetes, also known as insulin-dependent diabetes, is a chronic disease of blood glucose regulation (hemostasis), and is caused by the lack of insulin secretion from pancreatic cells." (PMID 32784179, 2020). "In this way, plasma insulin level is absolutely deficient in our STZ‐induced type 1 diabetic rats (data not shown), which is consistent with the decreased expression or activity of PDK1 in carotid artery of type 1 diabetic rats in our current study." (PMID 33108705, 2020). "In addition, the plasma insulin level in rats with type-1 diabetes was significantly (p < 0.01) lower (2.15 ± 0.98 μU/mL; n = 6) than that in normal rats (12.64 ± 3.19 μU/mL; n = 6)." (PMID 33233692, 2020). "However, our results point to the lung function impairment as an unsuspected complication in patients with type 1 diabetes, especially in those who need higher doses of basal insulin." (PMID 32344939, 2020). "We found that the insulin-treated persons with type 1 diabetes displayed a Th2-biased immune phenotype with a high proportion of effector CD4+ T cells and CD19+ B cells, and a downregulation of Th1 serum cytokines, irrespective of their capacity for glycemic control." (PMID 32626786, 2020). "In type 1 diabetes, cytokine-induced ER stress may account for impaired folding of insulin and altered HLA presentation of antigenic peptides thereof, hence contributing to beta cell dysfunction and T cell-mediated destruction." (PMID 32894308, 2020). "The majority of people with type 1 diabetes require lifelong insulin replacement therapy and have reduced life expectancy and quality of life; their treatment places a substantial economic burden on health services, with direct UK health costs estimated at £1bn in 2010–2011." (PMID 31980846, 2020). "Over 100 years ago, Joslin and Benedict noted that the metabolic rate in untreated insulin-deficient individuals with type 1 diabetes was roughly 15% higher compared with similar body weight subjects without type 1 diabetes." (PMID 32872407, 2020). "Next to its immunomodulatory role via Tregs, TNFR2 promotes apoptosis of insulin-specific pathogenic autoreactive CD8+ T cells but not normal T cells isolated from diabetes type I patients." (PMID 32528961, 2020). "Furthermore, physical activity has been shown to improve insulin sensitivity in type 1 diabetes, but the evidence regarding HbA1c lowering is so far controversial." (PMID 31749048, 2020). "Type 1 Diabetes Mellitus (T1D) is a multifactorial disease characterized by chronic hyperglycaemia that arises from a T cell-mediated autoimmune attack of the pancreatic β-cells and culminates with the suppression of insulin production." (PMID 32316573, 2020).